ARID1A (AT-rich interaction domain 1A)
Diseases named in the same sentence as ARID1A in open-access papers (continued):
Sharing a sentence is not in itself a finding about the gene and the disease.
ovarian carcinoma (continued). "Some of the molecular abnormalities encountered in endometriosis‐associated ovarian cancer include: the activation of oncogenic KRAS and PI3 K pathways and the inactivation of tumor suppressor genes PTEN and AT‐Rich Interaction Domain 1A (ARID1A)." (PMID 38962465, 2024). "Apart from our study, ARID1A deficiency was observed to induce a similar MMR phenotype, correlating with microsatellite instability-high (MSI-H) and higher TMB (TMB-H) in ovarian cancer." (PMID 38166741, 2024). "The alkylating agent temozolomide (TMZ) combined with PARP inhibition has also been shown to induce replication fork instability and apoptosis in ARID1A mutant ovarian cancer xenografts." (PMID 39272926, 2024). "The bioinformatic analysis reveals that PLAU is induced in ARID1A-depleted pancreatic cancer, ovarian cancer, and esophageal cancer cells." (PMID 38229120, 2024). "ARID1A deletion in ovarian cancer can transcriptionally activate MRP2 protein expression after chromatin remodeling, leading to multidrug resistance to carboplatin and paclitaxel in ovarian cancer." (PMID 39697230, 2024). "Inhibition of EZH2 has also been shown to be lethal for ARID1A mutant ovarian cancer cells due to the activation of the PI3K/AKT signaling pathway." (PMID 37093326, 2023). "Unexpectedly, ARID1A inactivation in association with APC and PTEN absence in mouse ovarian cancer models, prompted tumor cells towards epithelial differentiation." (PMID 36890819, 2023). "Endometriosis-associated ovarian cancers (EAOC), namely, clear cell and endometrioid histotypes, are known to harbor recurrent somatic driver mutations, for example, in ARID1A and PIK3CA." (PMID 37789421, 2023). "Recurrently mutated ovarian cancer driver genes, including LRP1B, KMT2A, ARID1A, KMT2C and ATRX were also found in two cell lines." (PMID 37525498, 2023). "The researchers found that in ovarian cancer cells with ARID1A mutation, PIK3IP1, a direct target gene of ARID1A and EZH2, was up-regulated after EZH2 was inhibited, leading to cell death by inhibiting the PI3K-AKT signaling pathway." (PMID 38008753, 2023). "The MMR germline carriers with endometrial cancer had more somatic MMR variants, while those with ovarian cancer harbored more common variants in driver genes, including KRAS, ARID1A, and PTEN." (PMID 37523182, 2023). "A study in ovarian cancer showed that ARID1A alterations may also mediate resistance to platinum chemotherapy and estrogen receptor degraders/modulators, which further supports our findings that ARID1A deficiency may render patients insensitive to initial chemotherapy and be associated with relapse." (PMID 37981695, 2023). "Combined inhibition of BRD4 with ATR/WEE1 is synergistic in ARID1A mutant clear cell ovarian cancer cells." (PMID 37841875, 2023). "ARID1A mutations have been found enriched in MSI-H neoplasms including endometrial carcinomas, ovarian carcinomas, gastric adenocarcinomas, colon cancers, and prostate cancers." (PMID 36123603, 2022). "Previous research has revealed that ARID1A mutation or ARID1A expression loss contributes to the dMMR subtype, higher PD-L1 expression and remodeling of the TIME, which leads to enhanced sensitivity to ICIs in ovarian cancer and gastric cancer." (PMID 36229854, 2022). "ARID1A-mutated ovarian clear cell carcinoma (OCCC) is a relatively indolent and chemoresistant ovarian cancer histotype." (PMID 36082022, 2022).
ovarian carcinoma (continued). "Ovarian cancer cell A2780 with ARID1A-deificiency and pancreatic cancer cell Hs700T with SMARCA4-deficiency were also moderately sensitive to MAK683." (PMID 35169119, 2022). "He and colleagues found that all 10 ovarian cancer patients with loss of ARID1A and BRCA-wild type from the study had significantly less PFS on rucaparib than proficient ARID1A cancers." (PMID 35626165, 2022). "The literature section indicates that ARID1A is observed in a variety of cancers including bladder cancer, ovarian cancer, liver cancer and colon cancer." (PMID 36035123, 2022). "Deleterious mutations in SWI/SNF chromatin remodeling genes, such as ARID1A, are present in more than 50% of cases of ovarian clear cell carcinoma (OCCC), a histological subtype of ovarian cancer prevalent in Asian countries." (PMID 33917230, 2021). "A recent study demonstrates that ARID1A plays a role in glucocorticoid-induced transcriptional co-activation in ovarian carcinomas." (PMID 34671561, 2021). "Other SWI/SNF altered cancers that are dependent on EZH2 include SS18-SSX translocated synovial sarcoma, ARID1A-mutated ovarian cancer, SMARCA4-mutated lung and ovarian cancers, and PBRM1-mutated renal cancers." (PMID 34617019, 2021). "Here, we report that knockdown of ARID1A expression in ovarian cancer cells expressing this protein results in increases in oxidative phosphorylation (OXPHOS)." (PMID 33947138, 2021). "Several studies have reported that HDAC inhibition make for increased PD-L1 expression in melanoma, ARID1A-inactivated Ovarian Cancer, and anaplastic thyroid cancer." (PMID 34064441, 2021). "The study demonstrated that ovarian cancer cell lines depleted of ARID1A exhibit decreased binding of Condensing-II at active enhancers." (PMID 33748136, 2021). "AT-rich interaction domain 1A (ARID1A) is a tumor suppressor gene that mutates in several cancer types, including breast cancer, ovarian cancer, and colorectal cancer (CRC)." (PMID 34414106, 2021). "ARID1A mutations were originally described at high frequency in ovarian clear cell carcinoma (OCCC), an uncommon but aggressive subtype of ovarian cancer." (PMID 32393201, 2020). "While ARID1A-deficiency also enhanced sensitivity 4-fold, RA375 was active against all ovarian cancer cell lines tested." (PMID 31940398, 2020). "Concomitant ARID1A/B alterations occur in ~25% of dedifferentiated endometrial and ovarian carcinomas." (PMID 32575483, 2020). "In vitro and in vivo studies have revealed an important link between ARID1A mutation status and SAHA sensitivity in ovarian cancer." (PMID 32429325, 2020). "In this review, we present the data demonstrating the co-occurrence of mutations of ARID1A and the PI3K pathway in our cohort of ovarian cancers from the Avera Cancer Institute (SD, USA)." (PMID 31731647, 2019). "We also studied the co-occurrence of ARID1A alterations with alterations of genes of the PI3K pathway in our patients with ovarian cancers." (PMID 31731647, 2019).
ovarian carcinoma (continued). "Consistently, ARID1A inactivation prolongs survival in an Apc- and Pten-defective mouse ovarian cancer model." (PMID 31492885, 2019). "Loss of ARID1A/BAF250a expression led to significantly high levels of AKT-Thr308 and AKT-Ser473 phosphorylation in chemotherapy-naive ovarian carcinomas." (PMID 31731647, 2019). "Genetic mutations in PTEN along with alterations of PIK3CA, PIK3R1, ARID1A, Wnt/β-catenin, microsatellite instability, SRC, and KRAS have been demonstrated to be critical in the pathogenesis of endometriosis-associated ovarian cancers." (PMID 31731647, 2019). "The pathogenesis of ovarian cancer is closely related to ARID1A (AT-rich interactive domain-containing protein 1A), which is present in up to 57% of patients and acts as a tumor suppressor in various cancers." (PMID 31241714, 2019). "ARID1A has been identified as a novel tumor suppressor gene in ovarian cancer and subsequently in various other tumor types." (PMID 31080553, 2019). "Pre-clinical work has identified ARID1A deficiency as a biomarker for the efficacy of ATR inhibitors, and in ovarian cancer cells, the multi-kinase inhibitor dasatinib." (PMID 30763338, 2019). "Components of the chromatin remodeling complexes, such as ARID1A (BAF250A) of the SWI/SNF complex and Rsf-1 of the ISWI complex, are mutated and/or overexpressed in ovarian cancer, respectively." (PMID 31426393, 2019). "Since ARID1A mutations are highly common in OCCC, we next tested synthetic lethality in different subtypes of ovarian carcinoma cell lines." (PMID 30097580, 2018). "We identify that ARID1A loss confers resistance to PARP inhibitors in cells and ovarian cancer patients and that loss of GPBP1 causes resistance to cisplatin and PARP inhibitors through the regulation of genes involved in homologous recombination." (PMID 29669295, 2018). "Concurrent ARID1A and ARID1B mutations were detected in the undifferentiated components of approximately one-quarter of dedifferentiated endometrial and ovarian carcinomas." (PMID 29890703, 2018). "Recent evidence shows that ARID1A gene silencing reduces the sensitivity of ovarian cancer to cisplatin via the regulation of AKT expression." (PMID 29392887, 2018). "Together these data suggest that the deletion of ARID1A and mutation in Pik3ca*H1057R results in increased IL6 expression leading to the ovarian surface epithelial hyperplasia and eventually clear cell ovarian cancer." (PMID 30087267, 2018). "Establishing the clinical relevance of ARID1A mutation and the role of ARID1B can lead to the development of more effective treatments for ovarian cancer." (PMID 29890703, 2018). "The contributions of both ARID1A and KRAS warrant further study in terms of endometriosis, the endometriotic tumor microenvironment, and endometriosis-associated ovarian cancer." (PMID 30087267, 2018). "BRD4 encoding a chromatin remodeler and MLL2 encoding a H3K4 methyltransferase were the top mutant genes in colorectal tumors (62 %) and ARID1A, a chromatin remodeler gene, in ovarian carcinomas (50 %)." (PMID 29296220, 2017). "Specifically, the effects of ARID1A versus ARID1B loss on the accessible genome are consistent with a higher frequency of ARID1A mutations in colorectal and ovarian carcinoma." (PMID 28967863, 2017). "To complement the siRNA experiments, we transiently re-expressed ARID1A in ARID1A-mutant TOV21G ovarian cancer cells and found that ARID1A re-expression resulted in increased resistance of the cells to treatment with elesclomol." (PMID 27486766, 2016). "Knockdown of ARID1A in RMG1 and OVCA432 ovarian cancer cells resulted in increased sensitivity to elesclomol, whereas restoration of ARID1A expression in TOV21G ovarian cancer cells resulted in increased resistance to elesclomol." (PMID 27486766, 2016). "Although mutations in PIK3CA, KRAS, PTEN, BRAF and ARID1A are uncommon in HGSOC, they are characteristic of other ovarian cancer subtypes." (PMID 23839242, 2013).
ovarian carcinoma (continued). "Likewise, in ARID1A mutant ovarian cancer models, simvastatin and atorvastatin elicit pyroptosis and synergize with anti-PD-L1 therapy." (PMID 40171265, 2025). "Interestingly, ARID1A is mutated in the benign condition endometriosis, with OCCC and EnOC described as endometriosis-associated ovarian cancers (EAOC)." (PMID 39272926, 2024). "The enigmatic function of Arid1a in cancer has been studied most frequently in ovarian cancer." (PMID 39123453, 2024). "This sensitivity was also seen in ARID1A-mutant ovarian cancer cells, and that may in part be due to BETi downregulating ARID1B, a known synthetic lethal event for cells harboring ARID1A loss." (PMID 38060314, 2024). "Inhibition of methyltransferase Repressive Complex 2 Subunit(EZH2)and acetyltransferase Histone Deacetylase(HDAC), which are involved in regulating histone modifications, can lead to tumor regression in AT-Rich Interaction Domain 1A (ARID1A) mutant ovarian cancer mouse models." (PMID 39445058, 2024). "The ARID1A gene, encoding a crucial component of the SWI/SNF complex, is considered a tumor suppressor gene and is frequently mutated in various cancers, with the highest mutation rates found in the two ovarian cancers associated with endometriosis." (PMID 38725626, 2024). "We, therefore, tested the sensitivity of additional ARID1A-mutant or endometriosis-related ovarian cancer cell lines to tolinapant and entinostat to evaluate whether these characteristics might serve as markers for sensitivity to SMAC mimetics." (PMID 36831656, 2023). "Currently, clinical trials for ovarian cancer using ARID1A as a biomarker are underway." (PMID 38275587, 2023). "A similar effect was also observed in various ARID1A mutant ovarian cancer cell lines and mice." (PMID 37093326, 2023). "Therapeutic strategies for ARID1A-mutant ovarian cancers are limited." (PMID 37238613, 2023). "Not surprisingly, this synthetic lethality relationship appears to be absent in certain subtypes of cancers harboring ARID1A mutations, such as endometrial/uterine cancer, pancreatic cancer, ovarian cancer, lung cancer and colon cancer." (PMID 36980292, 2023). "ARID1A mutational status is considered to hold prognostic significance in a range of solid malignancies, yet in endometriosis‐related ovarian carcinomas there has been a lack of clarity of its prognostic role." (PMID 35647895, 2022). "In mice with ARID1A‐deficient ovarian cancer, the therapeutic effect of PD‐L1 inhibitors was greatly enhanced, suggesting ICI treatment could be beneficial for ARID1A‐impaired patients." (PMID 34042312, 2022). "The study definitively showed that ARID1A status does not provide any independent prognostic value in endometriosis‐associated ovarian carcinomas." (PMID 35647895, 2022).
ovarian carcinoma (continued). "Driver mutations in KRAS, PIK3CA, PTEN, PPP2R1A, and ARID1A presented as larger clones than non-driver mutations and with similar frequency in lavages from patients with and without ovarian cancer, indicating prevalent somatic evolution in all patients." (PMID 36311816, 2022). "Although ARID1A alterations occur in ~30–50% of ovarian clear cell carcinomas, ovarian clear cell cancers are a rare subset of ovarian cancer, and only one patient was designated with this pathologic entity in the dataset; hence, the frequency of ARID1A mutations in this histology was not evaluable." (PMID 36077815, 2022). "Some studies have described a spatial and chronological association with transformation of atypical endometriosis to ovarian cancer and, molecular studies have detected similar genetic alterations (e.g. mutations of ARID1A and PIK3CA) in endometriosis and in ovarian cancer of clear cell histology." (PMID 34185779, 2021). "Indeed, the BAF components ARID1A and SMARCA2/4 are persistently mutated in ovarian cancer subtypes, and represent promising sensitivities for epigenetic inhibition therapy." (PMID 34213777, 2021). "In addition, ARID1A-mutant ovarian cancers are sensitive to a combined therapy of exogenous irradiation and PARP inhibition because of a reduced efficiency of the non-homologous end-joining (NHEJ) machinery to repair DNA lesions." (PMID 33941852, 2021). "Indeed, ARID1A‐mutant ovarian cancer cell lines OVISE and TOV21G have displayed sensitivity to EZH2 inhibition, and in wild‐type ARID1A cells, its knockdown confers EZH2 sensitivity." (PMID 34213777, 2021). "Moreover, ARID1A mutant tumours have been shown to demonstrate activation of the immune checkpoint pathway and sensitization to the PD-1/PD-L1 checkpoint blockade in ovarian cancer in in vivo mouse models." (PMID 34359755, 2021). "Finally, SAHA treatment of several ARID1A KO compared to WT ovarian cancer cells have revealed an important decrease in terms of IC50 value of approximately 100 fold." (PMID 32429325, 2020). "The mechanism of ARID1A loss, which occurs specifically in endometriosis-associated ovarian cancer but not in ovarian endometriosis, is an important key for elucidating the pathogenesis of the malignant transformation of ovarian endometriosis." (PMID 32868822, 2020). "Several studies have focused on ARID1A protein expression in endometriosis or ovarian cancer." (PMID 32868822, 2020). "Indeed loss of ARID1B in ARID1A-deficient cells destabilizes the SWI/SNF complex and impairs proliferation in gastric and ovarian cancers." (PMID 32967217, 2020). "Based on the previous research, we hypothesized that FRBI impacts the expression levels and production of ARID1A, PTEN, and FSHR, which are associated with carcinogenesis and progression of ovarian cancer." (PMID 31241714, 2019). "We present alterations of the ARID1A gene in tumors from patients with ovarian cancers." (PMID 31731647, 2019). "Surprisingly none of our ARID1A alterations in patients with ovarian cancers were companied by high tumor mutation burden (TMB) or microsatellite instability (MSI), albeit our sample number is less." (PMID 31731647, 2019). "Finally, targeting HDAC activity, particularly HDAC2, blocks the progression of Arid1a mutant ovarian cancer cells." (PMID 31123059, 2019). "In this case, ARID1A heterozygosity may suffice for oncogenesis during points of low ARID1A expression, which may account for the ARID1A genetic differences observed between the present mouse model and epithelial ovarian cancer models." (PMID 31391455, 2019). "Significantly better survival in the subgroup of ARID1A positive tumors could also be observed for sole analysis of all endometrioid (p = 0.039) and all ovarian carcinoma (p = 0.008) as well as tumors of grading G3 (p = 0.028)." (PMID 29451900, 2018).